MDM2 (MDM2 proto-oncogene)
Diseases named in the same sentence as MDM2 in open-access papers (continued):
Sharing a sentence is not in itself a finding about the gene and the disease.
colorectal cancer (continued). "Evidence indicates that MDM2 SNP309 genetic variation might confer poor outcomes in colorectal cancer and chronic lymphocytic leukemia." (PMID 22844496, 2012). "Upregulation of DDLPS MDM2 by GP130 signal transduction may be facilitated by STAT1 and STAT3 transcription factors, as seen in colorectal cancer where GP130 activation by IL6 cytokine family member leukemia inhibitory factor led to increased MDM2 levels in a STAT3-dependent fashion." (PMID 40961077, 2025). "Furthermore, a significant inverse correlation between miR-1827 and MDM2 mRNA expression in these colorectal cancer samples was observed (p = 0.0029), which strongly suggests that the down-regulation of miR-1827 increases MDM2 expression in human colorectal cancer." (PMID 26840028, 2016). "Hinokiflavone induced a bidirectional MDM2 and MDMX response in leukemia and colorectal cancer cells." (PMID 35625571, 2022). "For example, the downregulation of miRNA-339-5p (hereafter miRNA-339) was observed in colorectal cancer and breast cancer, and it was later demonstrated that this miRNA was able to bind the 3′ UTR of MDM2 mRNA in human colorectal cancer cells." (PMID 34065345, 2021). "MiR-194, commonly repressed in colorectal cancer, suppresses tumor growth by regulating the MAP4K4/c-Jun/MDM2 signaling pathway." (PMID 26909612, 2016). "Another study had similar findings regarding the role of miR-194 in colorectal carcinoma, though it suggested that miR-194 regulated the MAP4K4/c-Jun/MDM2 signaling pathway." (PMID 26909612, 2016). "The expression of MDM2 and RASSF10 was evaluated by immunohistochemistry in 27 available cases of human primary colorectal cancer." (PMID 25638156, 2015). "In 7 cases of human primary colorectal cancer with high level expression of RASSF10, the expression of MDM2 was diminished." (PMID 25638156, 2015). "Finally, we demonstrated that NFATc1 inhibitors suppress colorectal cancer (CRC) growth by targeting the NFATc1/NADK and NFATc1/MDM2 axis and synergize with oxaliplatin." (PMID 41203626, 2025).
colorectal cancer (continued). "Overall, DUSP6, MDM2, and EIF2S3 were consistently selected as significant factors associated with colorectal cancer in all logistic models and were not modulated by any other genes or clusters." (PMID 36672653, 2023).
prostate carcinoma (106 papers, 2008 to 2025). A carcinoma that arises from epithelial cells of the prostate gland. "We examined the frequencies of CCND1 and MDM2 copy number gains in cases with CDK12 mutations in the public data on advanced prostate cancer and found these to be 50% and 23%, respectively, which is generally consistent with our data." (PMID 36271301, 2022). "The present study was designed to test a natural MDM2 inhibitor, Inulanolide A (InuA), for anti-prostate cancer activity and to determine the underlying mechanism(s) of action." (PMID 29311926, 2017). "MDM2 is overexpressed in many tumors including prostate cancer, and it is associated with radiation resistance." (PMID 23351141, 2013). "Additionally, MDM2 overexpression correlates with metastasis and advanced forms of several cancers, including colon, breast, and prostate cancers, and MDM2 overexpression is often associated with drug resistance." (PMID 40521302, 2025). "Abnormal expression of MDM2 in prostate cancer is associated with aggressive behavior." (PMID 36230846, 2022). "Although overexpression of MDM2 has been linked to advanced stages of prostate cancer, the role of MDMX in prostate cancer progression remains unclear." (PMID 29464071, 2018). "Moreover, emodin, a natural compound present in Japanese knotweed and rhubarb, is known to induce AR protein degradation by increasing the association between AR and Mdm2, and also to suppress prostate cancer growth in both in vitro and in vivo models." (PMID 29707137, 2018). "A more recent analysis of this trial data indicated that high expression of COX-2 in prostate cancer, in combination with three other genes (ki-67, MDM2 and p16), predicted for an increased risk of developing distant metastases following androgen deprivation therapy and radiotherapy." (PMID 26068950, 2015). "On the other hand, endocrine resistance and prostate cancer pathways are highlighted by genes such as MDM2 and LEF1, Oncogene-induced senescence, and MDM2 and ETS1." (PMID 40621499, 2025). "MDM2 is known to mediate the ubiquitination and degradation of AR, where MDM2 knockout results in increased AR expression in prostate cancer cells." (PMID 39960347, 2025).
prostate carcinoma (continued). "Others have previously shown that PAK6 phosphorylates MDM2 at the Ser186 and Thr158 sites, activating MDM2 to ubiquitinate the androgen receptor and inhibit tumor growth in prostate cancer cells." (PMID 40650306, 2025). "The results suggest that MDM2 is an E3 ligase inducing AR polyubiquitination and protein degradation in prostate cancer cells." (PMID 38410785, 2024). "Since MDM2 inhibition increased the AR and AR-V7 protein levels, MDM2 inhibition is expected to affect the growth of prostate cancer cells." (PMID 38410785, 2024). "Mouse double minute 2 (MDM2) has been shown to act as an oncogene in a variety of tumors, including prostate cancer." (PMID 38200609, 2024). "In support of this direct effect, we determined here that MDM2 affects the ubiquitination status of TM4SF3, and MDM2 interacts with TM4SF3 in prostate cancer cells." (PMID 38410785, 2024). "Since AR is involved in prostate cancer cell migration, we were interested to determine if MDM2 inhibition would affect these processes." (PMID 38410785, 2024). "In this way, it brings together AR, the key driver of prostate cancer, and MDM2 (mouse double minute 2 gene), an E3 ubiquitin ligase leading to ubiquitination and subsequent degradation of f-AR and AR-V7 in prostate cancer cells." (PMID 39598525, 2024). "The results collectively show that MDM2 inhibition markedly enhances the migration of prostate cancer cells, which are likely mediated by the positive effect of MDM2i on AR, AR-V7, and TM4SF3 proteins." (PMID 38410785, 2024). "In UCEC, MDM2 oncogene expression was higher in White samples, a result consistent with the reported elevation of MDM2 protein expression in Caucasian Americans when compared to African Americans in prostate cancer." (PMID 37345032, 2023). "The interaction promotes MDM2-mediated ubiquitination of AR and its subsequent proteasomal degradation resulting in growth inhibition of prostate cancer cells." (PMID 36831540, 2023). "In this study, we demonstrate the potential role of VNPP433-3β as molecular glue that induces physical proximity between the Androgen Receptor and MDM2 E3 ligase in prostate cancer cells." (PMID 36831540, 2023). "In this study, we demonstrate the potential role of VNPP433-3β as molecular glue in promoting targeted degradation of f-AR in prostate cancer cells by induced proximity with the E3 ligase MDM2." (PMID 36831540, 2023). "MDM2 inhibitor (XR-2) possesses potently prostate cancer progresses inhibition activity both in vitro and in vivo." (PMID 35548335, 2022).
prostate carcinoma (continued). "In 22RV1 cells, a prostate cancer cell line that MD-224 did degrade MDM2 under our experimental condition, and TPEN induced MDMX degradation with or without MD-224 treatment." (PMID 34627839, 2021). "First, the expression profiles of five key radiation-responsive genes (FDXR, SESN1, GADD45, DDB2, and MDM2) during the course of RT in the blood of 8 prostate cancer patients treated with IMRT and SABR were analyzed." (PMID 32519025, 2020). "Our results are consistent with other studies showing that another curcumin analog, ASC-J9, induces MDM2-mediated AR ubiquitination to inhibit prostate cancer, suggesting that AR is a critical player for anti-cancer effects of curcumin and its analogs." (PMID 31896509, 2020). "We tested colon and prostate cancer cell lines for the expression of MDM2 and their sensitivity to RITA with anticancer drugs." (PMID 31759358, 2019). "Other studies confirmed treatment of prostate cancer cells with MI-219, an inhibitor of MDM2 results in tumor sensitization to radiation or androgen deprivation therapy in vitro and in vivo." (PMID 31366128, 2019). "AR is a direct target for MDM2-mediated ubiquitylation in prostate cancer cells Of interest, MDM2 activation by phosphorylation is negatively regulated by the downstream target genes of AR signaling." (PMID 29713287, 2018). "BMI1 binds the androgen receptor (AR) and prevents MDM2-mediated AR protein degradation, resulting in sustained AR signaling in prostate cancer cells." (PMID 29402932, 2018). "Together, our results indicate that MDMX regulates the AR stability in prostate cancer cells by modulating the MDM2 E3 ligase function towards AR." (PMID 29464071, 2018). "InuA was further assessed for its inhibitory effects on MDM2 P2 promoter activity in prostate cancer cells transfected with dominant-negative NFAT (DN-NFAT)." (PMID 29311926, 2017). "In summary, InuA represents a novel class of bifunctional MDM2 inhibitors, and should be further investigated as a candidate lead compound for prostate cancer prevention and therapy." (PMID 29311926, 2017). "In the present study, we assessed the anticancer activity of a novel bifunctional MDM2 inhibitor, InuA, and investigated its dual mechanisms of action in human prostate cancer models." (PMID 29311926, 2017). "Because MDMX protein was also destabilized in response to InuA treatment in prostate cancer cells, it is at least partially responsible for the InuA-induced MDM2 destabilization." (PMID 29311926, 2017).